IL6 (interleukin 6)
Diseases named in the same sentence as IL6 in open-access papers (continued):
Sharing a sentence is not in itself a finding about the gene and the disease.
neurological diseases (133 papers, 2010 to 2026). "Specifically, 2-DG reduced the expression of the inflammatory genes C3, TNFα, LCN2, and IL6, all of which are implicated in various neurodegenerative and neurological diseases." (PMID 35326266, 2022). "Another pro-inflammatory cytokine is TNFα known to interact with IL6 and is associated with neuro-inflammatory response that is linked with several neurological disorders." (PMID 33627134, 2021). "The increased levels of IL‐6 and IL‐1 were recognized as the main cause of the severity of neurological disorders in the Nrf2 knockout mice after SCI." (PMID 34423582, 2021). "Receiver-operating characteristic analysisrevealed increased levels of cerebrospinal fluid interleukin-6, seruminterleukin-8 and growth-regulated oncogene-α in most patients withautoantibody-associated neurological diseases." (PMID 31205739, 2019). "Meanwhile, IL-6 overexpression in the brain of transgenic mice has been shown to cause severe neurological disease." (PMID 28373844, 2017). "Elevated levels of IL-6 in the CNS have been reported in a number of neurological diseases that are associated with brain injury or inflammation." (PMID 28486989, 2017). "The neurologic disease has been associated with high proviral load and increased levels of proinflammatory cytokines including IL-1, IL-6, TNF-α, and IFN-γ." (PMID 26904697, 2016). "Wnt5a was also involved in Human Immunodeficiency Virus (HIV) associated neurological disorders by promoting IL-1β, IL-6 and TNF-α production in the spinal cord." (PMID 24993819, 2014). "In addition, elevated levels of IL-6 are linked to increased levels of Th17/Treg ratio, which disrupts the immune tolerance in the brain cells and causes neurological disorders." (PMID 40843259, 2025). "IL6 is a pleiotropic cytokine implicated in several nervous system disorders." (PMID 35193620, 2022). "In this case, IL-6 is considered to have anti-inflammatory effects and may be a factor in reducing the risk of chronic inflammation and neurological diseases by exercising regularly." (PMID 35645781, 2022). "The potential involvement of the NF-κB pathway was investigated because the promoters for both IL-6 and IL-8 contain a binding site for NF-κB and this transcription factor is known to be involved in neurological disorders associated with increased inflammation." (PMID 22420994, 2012). "In this context, IL-6 is rather assumed to have an anti-inflammatory effect and could be a factor by which regular exercise might reduce chronic (low-grade) inflammation and the risk for neurological disorders." (PMID 34823469, 2021). "Interleukin-6 (IL-6) is a core neuroinflammatory mediator, yet its expression profile across the full spectrum of neurological disorders remains poorly characterized in large-scale cohorts using a uniform detection platform." (PMID 42212133, 2026). "They attenuate inflammation-induced disorders such as cardiovascular and neurological disorders via down-regulating pro-inflammatory cytokines (IL-6, CRP, COX-2, LPO, TGF-β1, NF-κB, and TNF-α), and pathways (IRAK4, MAPK, JAK/STAT3, TLR4, and ERK)." (PMID 41640995, 2026). "In summary, we demonstrate that subclinical levels of IFN-α can markedly exacerbate IL-6-mediated neurological disease, suggesting that future studies, should consider the combined effects of IL-6 and IFN-α." (PMID 40613088, 2025). "Chronic production of certain cytokines (e.g., IL-6) in the central nervous system is responsible for the development of human neurological disorders." (PMID 40746414, 2025). "COX-2, increased IL-10 and TGF-β1 in the brain tissue of rats and reduced plasma cytokines TNF-α, IL-1β, IL-2, IL-3, IL-4, IL-5, IL-6, etc. and exotoxin activity in plasma of different neurological disorders." (PMID 40297338, 2025). "Production of TNF, IL-6, and NO by microglia contributes to neurodegeneration and inflammation in these neurological diseases." (PMID 39000243, 2024).
neurological diseases (continued). "This therapeutic approach highlights the importance of targeting IL-6 and other inflammatory mediators to alleviate neuroinflammation and its adverse effects on neurological disorders." (PMID 39015561, 2024). "In the intricate landscape of neuroinflammation, both MSCs and IL-6 wield substantial influence, jointly shaping the pathophysiology of diverse neurological disorders." (PMID 39015561, 2024). "Conversely, elevated levels of IL-6 have been observed in both plasma and brain tissue in various neurological disorders." (PMID 39126046, 2024). "This review provides a comprehensive overview of IL-6’s involvement in neurological disorders, examining endogenous IL-6 and IL-6 derived from MSCs." (PMID 39015561, 2024). "By elucidating IL-6’s interplay with neurological pathologies, this review offers insights into novel therapeutic strategies targeting IL-6 signaling pathways for neurological disorders." (PMID 39015561, 2024). "On the contrary, neurological presentations were inversely associated with markers of disease severity such as IL-6, TNF-α, IL-10/CXCL10, CRP, D-dimer, and LDH, all of which were significantly lower in patients with neurological diseases." (PMID 36851766, 2023). "This higher level of IL-6 in CSF samples of NMO patients compared to MS was also supported by another study, where the IL-6 level was found to be remarkably higher than that in MS and other neurological diseases (p < 0.001)." (PMID 37175665, 2023). "Maternal intrauterine infection associated with increased levels of pro-inflammatory cytokines (IL-6, TNF-α, IL-1β) is the most important cause of preterm birth and neonatal neurological disorders." (PMID 35155393, 2022). "Increased level of IL‐6 has been reported in several neurological diseases, suggesting the neuropathological role of IL‐6." (PMID 37786746, 2022). "IL-6 is a pro-inflammatory cytokine that is frequently accompanied by different neurological diseases and leads to astrogliosis." (PMID 35745768, 2022). "To further understand the role of SBNO2 in the CNS and, in particular, in IL-6-mediated neurological disease, we generated a new mouse model with disruption of Sbno2 and crossed these mice with the GFAP-IL6 transgenic mice." (PMID 35624480, 2022). "Recent research indicates that the peripheral levels of IL-6 are higher compared with those healthy people in those patients with neurological diseases or injuries." (PMID 36353359, 2022). "Of particular interest is the fact that over-expression of IL-6 has been shown to produce neurologic disease in mouse, activating astrocytes and microglia." (PMID 33540568, 2021). "The analyzed cytokines Il1b, Il6, Tnfa, and Tgfb all play important roles in various neurological disorders and have multiple functions involving cell differentiation, growth, and survival." (PMID 32833183, 2021). "Signaling pathways with reported roles in TBI and other neurological diseases were also enriched, including IL-6/IL8 signaling, ERK/MAPK signaling, Rho GTPase signaling, integrin signaling, RhoGDI signaling, and NFKB signaling." (PMID 33668155, 2021). "A considerable body of data has been compiled regarding IL-6, in which IL-6 is described as a pro-inflammatory cytokine in chronic inflammation models that produces neurologic diseases in mice." (PMID 32806582, 2020). "The over-production of IL-1β, IL-6, and TNF-α cytokines is a hallmark of neurological diseases in the brain." (PMID 31835609, 2019). "Proinflammatory cytokines, including TNF-α and IL-6, are produced after microglial activation and their abnormal production or functions in the brain are characteristic of various neurological diseases." (PMID 31336605, 2019). "Normalizing IL-6 production and its levels is likely a better strategy to treat numerous neurological disorders observed in anti-NMDAR encephalitis." (PMID 31297084, 2019).
neurological diseases (continued). "High levels of pro-inflammatory cytokines such as TNF-α, IL-6, and IL-1β were found elevated in the brain tissue from patients with neurological diseases." (PMID 29719536, 2018). "The potential involvement of NF-κB and STAT3 was investigated because the promoters of both TNFα and IL-6 contain binding sites for NF-κB and STAT3, which are known to be involved in neurological disorders associated with increased inflammation." (PMID 29228978, 2017). "Previous studies on neurological disease models indicate that IL-6 can accelerate or decelerate neuronal regeneration in a context-dependent manner." (PMID 27070121, 2016). "Previous studies have shown that the increased production of proinflammatory cytokines including interleukin-6 (IL-6), IL-1β, and TNF-α are associated with the severity of EV71-induced neurological diseases." (PMID 26610549, 2015). "In line with this, elevated brain protein levels of TNF-α, IL-1β, and IL-6 have been reported in rodent mTBI models as well as within human CSF within hours of injury, as they have in other neurological disorders." (PMID 25879458, 2015). "The involvement of IL-6 with nervous system diseases has been an area of increasing focus, and IL-6 is generally recognized to exhibit neuroprotective effects." (PMID 24348794, 2014). "Elevated serum IL-6 levels were detected in patients with neurological disorders, musculoskeletal injuries, and autoimmune and inflammatory conditions." (PMID 22778699, 2012). "IL6 is another pro-inflammatory cytokine present in the brain, typically at low levels; however, its synthesis increases substantially during PD and other neurological disorders." (PMID 41601963, 2026). "Dysregulation of IL-6 signaling within these regions, such as the hippocampus, cortex, striatum, and substantia nigra, can significantly affect neurological function and contribute to the manifestation of various symptoms observed in neurological disorders." (PMID 39015561, 2024). "Likewise, IL-6 plays an important role in glial activation during brain injury and its increased expression is often observed in several neurological disorders." (PMID 36140216, 2022). "Here, we demonstrate that SBNO2 is required to constrain IL-6-driven neurological disease." (PMID 35624480, 2022). "Interleukin-6 (IL-6) CSF levels were determined in 14 samples from 14 patients (CNS involvement in 13) in group I and were found to be elevated in 11 (79%; 10 × B/SC subgroup; 10 x “severe” neurological disease) according to the manufacturers’ cut-off." (PMID 35057809, 2022). "In contrast, the ratios between IL-22 and IL-6 or IL-8 were not appropriated to discriminate the risk for neurological disease." (PMID 33776990, 2021). "Digestive-system releases, hypersensitivity, male urogenital releases, and nervous-system diseases were also enriched by genes regulated by IL-6, so we could consider a combination of these diseases in the CRS elicited by IL-6." (PMID 33520118, 2021). "SOD1 TG/IL-6(-/-) mice (n = 17) were compared with SOD1 TG/IL-6(+/-) mice (n = 18), SOD1 TG/IL-6(+/+) mice (n = 11), WT mice (n = 15), IL-6(+/-) mice (n = 5) and IL-6(-/-) mice (n = 8), with respect to neurological disease severity score, body weight and the survival." (PMID 27070121, 2016). "The condition of our patient, therefore, might be analogous to the neurological disease induced in transgenic mice by IL-6 cerebral overexpression." (PMID 23432807, 2013). "In this context, anti-IL-6 therapy may be effective in this intractable neurologic disease." (PMID 28438224, 2017). "This may shift the effects of IL-6 toward pathological signaling in the brain, indicating a need for a more comprehensive understanding of exercise protocols related to IL-6 signaling, which could present additional therapeutic opportunities for treating neurological disorders." (PMID 40843259, 2025).
neurological diseases (continued). "IL-6 derived from MSCs, along with other bioactive factors secreted by them, promises to enhance the therapeutic efficacy of MSC-based treatments in neurological disorders, contributing to neuroprotection, neuroregeneration, and immunomodulation in the CNS." (PMID 39015561, 2024). "The level of 4 cytokines (TNF-α, IFN-α, IL-6, and monokine induced by IFN-γ) were found to be significantly higher in CHIKV patients with neurological diseases." (PMID 38229040, 2024). "PHBs can prevent apoptosis, inflammation, mitochondrial dysfunction, and autophagy in neurological disorders through different molecules and pathways, such as OPA-1, PINK1/Parkin, IL6/STAT3, Tau, NO, LC3, and TDP43." (PMID 35847581, 2022). "However, in some conditions, studies have found that cytokines such as TNFα, IL-1β, and IL-6 can also improve the outcome of diseases such as ADs and that neutralizing or knocking out these cytokines can eventually attenuate the progression of neurological diseases or injuries." (PMID 36353359, 2022). "Elevated IL-6 and IL-17A in D2R specific T-cells from subset of patients with SC, TS or PANS were seen compared to controls with neurological disease." (PMID 36061386, 2022). "Recent work has shown that blocking pro-inflammatory cytokines, including TNFα, IL-1β, and IL-6, can reduce the permeability of BBB and improve the outcomes of neurological diseases and injuries to a great extent." (PMID 36353359, 2022). "The stimulus-specific responses of microglia reflect known functional and pathological roles of IL-6 versus IFN-α in the brain and likely impart these cells with their unique functions in IL-6 versus IFN-α-mediated neurological disease." (PMID 35429976, 2022). "Chronically elevated IL-6 levels in the CNS due to IL-6 overexpression in astrocytes in transgenic mice promotes microglial density, inflammation exemplified by increased IL-1β, TNF, IL-10, IL-6 and MHCII expression, and neurologic disease." (PMID 34201844, 2021). "Of all secreted cytokines, both in experimental and clinical conditions, tumor necrosis factor alpha (TNF-α) together with interleukin 1 beta (IL-1β) and interleukin 6 (IL-6) dominate in the pathogenesis of SCI and other neurological diseases." (PMID 32801994, 2020). "EA can effectively reduce the levels of interleukin-1β (IL-1β), interleukin-6 (IL-6), interleukin-18 (IL-18), and tumor necrosis factor-α (TNF-α), helping to inhibit the inflammatory response in a variety of neurological diseases." (PMID 33204250, 2020). "Their connectivity map included interleukin-6 (IL-6) and tumour necrosis factor α (TNF-α) as central nodes and the pathway identified with the highest score was involved in neurological disease, psychological disorders, and cellular movement." (PMID 29301248, 2018). "Cytokines, growth factors and oxidative stress enzymes such as TWEAK, IL-6, IGF binding protein (IGFBP), and SOD were found to be involved in the network related to drug metabolism, neurological disease, organismal injury and abnormalities." (PMID 20967264, 2010). "Thus, administering PEFPs reduced IL-6, TNF-α, and IL-1β in hippocampal cells, inhibited the TNF-α and reduced NF-kB in the brain in different neurological disease models." (PMID 40297338, 2025). "Thus, IL-6, and MSC-derived IL-6 emerges as a key player in both the pathophysiology of neurological disorders and potential therapeutic interventions." (PMID 39015561, 2024). "In addition to major cytokines, such as TNFα, IL-1β, IL-6, and their receptors, other cytokines also play an important role in neuroinflammation and neurodegeneration and may provide some promising new targets for clinical application to treat neurological disease and injury." (PMID 36353359, 2022). "Since IL-6 is an important cytokine in neuroinflammation, our results support the notion that CBD may be useful in treating some neurological disorders." (PMID 33984046, 2021).
neurological diseases (continued). "It has been shown that DENV-2 induced IL-6, IFN-γ, and IL-10, and quercetin, naringin, catechin, and fisetin can change signaling pathways in the innate response to reduce neurological disorders being hopeful candidates for therapy of neurological disorders." (PMID 34764869, 2021). "Upregulated NLRP3 expression may enhance caspase-1-mediated inflammatory cascades and further stimulate the production of downstream inflammatory molecules, including IL-1β, IL-6, and TNF-α, all of which lead to an inflammatory response in a variety of neurological diseases." (PMID 36364939, 2022). "The role of IL-6 signaling in neurological diseases has not been completely clarified and may vary depending on the disease stages, on the ratio of free IL-6 and sIL-6R or other factors specific for each disease." (PMID 28798369, 2017). "Thus, the IL-6 levels in ADEs may not be suitable to help discriminate ALS from other neurological diseases." (PMID 31231184, 2019). "Serum IL-6, LDH, ferritin, hs-troponin I, CRP, procalcitonin, and D-dimers measured within 6 h of hospital admission for neurological disorder were analyzed and compared between survivors and non-survivors." (PMID 41751490, 2026). "An age-related increase in systemic IL-6/GlycA levels reveals inflammaging in PLHTLV-1, in the absence of neurological disease." (PMID 36482436, 2022). "This theory is supported by significantly elevated levels of serum cytokines IL‐6, TNF‐alpha, and IL‐10 in patients with IAE compared to those with no neurological disorders or not infected with influenza virus." (PMID 33155427, 2021). "Contrary to the healthy controls with no neurological disease, one study that evaluated serum inflammatory markers revealed significantly increased TNF-α, IL-6, and leptin levels in patients with PPS." (PMID 25886512, 2015).